LPAR1 (lysophosphatidic acid receptor 1)
Diseases named in the same sentence as LPAR1 in open-access papers (continued):
Sharing a sentence is not in itself a finding about the gene and the disease.
Cirrhosis (3 papers, 2016 to 2020). A chronic disorder of the liver in which liver tissue becomes scarred and is partially replaced by regenerative nodules and fibrotic tissue resulting in loss of liver function. "According to a study, LPAR1, 3 and 6 expression is increased in the livers of patients with HCC, and underlying cirrhosis or HCV infection, compared to healthy livers with LPAR6 expression being stronger in HCC tissue than in paired non-tumor liver tissue." (PMID 31652837, 2019). "In a DEN model of cirrhosis, LPAR1 upregulation coincided with the development of cirrhosis." (PMID 33255794, 2020).
cognitive deficits (3 papers, 2019 to 2025). "LPAR1 was associated with cognitive deficits and negative behavioral deficits in mouse models with ASD." (PMID 40873676, 2025). "For instance, LPAR1 null mice display a variety of negative behavioral signs and cognitive deficits including the traits commonly seen in AUT and SCZ patients." (PMID 31127088, 2019).
Hypertension (3 papers, 2012 to 2021). The presence of chronic increased pressure in the systemic arterial system. "Together with the LPAR1 findings, these results suggest alterations in inflammatory pathways including monocyte/macrophage function may be particularly important in OSA pathogenesis among AAs as well as the possibility of overlapping pathways that may mediate both hypertension and OSA." (PMID 23155414, 2012).
injury (3 papers, 2016 to 2025). Damage inflicted on the body as the direct or indirect result of an external force, with or without disruption of structural continuity. "In summary, the activation of the LPAR1/RhoA/ROCK pathway drives demyelination in the DRG, thereby playing a significant role in the development of allodynia and hyperalgesia following nerve injury." (PMID 40249935, 2025). "This study further established that LPAR1/RhoA/ROCK signaling mediates NMDA receptor activation by modulating ephrinB1, thereby initiating behaviors indicative of neuropathic pain following nerve injury." (PMID 40249935, 2025).
liver cancer (3 papers, 2013 to 2021). An epithelial or non-epithelial malignant neoplasm that arises from the liver. "Mutations of LPAR1 have been identified in lung and liver cancers in rat models exposed to carcinogen." (PMID 24147068, 2013).
pneumonia (3 papers, 2021 to 2024). An acute, acute and chronic, or chronic inflammation focally or diffusely affecting the lung parenchyma, caused by an infection in one or both of the lungs (by bacteria, viruses, fungi, or mycoplasma.). "It is noteworthy that in previous studies LPAR1 rather than LPAR2 was shown to promote neutrophil migration in pneumonia and production of the neutrophil chemoattractant IL-8 in human bronchial epithelial cells." (PMID 37816857, 2024).
type 1 diabetic (3 papers, 2016 to 2023). "We previously reported that STZ-induced type 1 diabetic mice exhibited weight loss, increased kidney weight, worsened renal function, upregulation of LPAR1 expression, and inflammation in the kidneys." (PMID 37373116, 2023). "Similarly, an LPAR1 inhibitor, AM095, inhibits the expression of proinflammatory cytokines and fibrotic factors in the kidney, reduces glomerular matrix expansion, and improves kidney function in a streptozotocin-induced type 1 diabetic model." (PMID 35806457, 2022).
type 2 diabetes (3 papers, 2021 to 2025). "Although the antagonism of LPAR1/3 protects against podocyte loss in endothelial nitric oxide synthase (eNOS)−/− db/db mice, a type 2 diabetes model, the role of LPA/LPAR1 signaling in podocyte damage during DN remains unexplored." (PMID 37373116, 2023).
brain cancer (2 papers, 2021 to 2022). A primary or metastatic malignant neoplasm affecting the brain. "Lpar1 deletion can cause neurodevelopmental disorders and CNS diseases, including brain cancer, neuropsychiatric disorders, demyelination diseases, and neuropathic pain." (PMID 34385905, 2021). "Lpar1 deletion causes neurodevelopmental disorders and CNS diseases, such as brain cancer, neuropsychiatric disorders, demyelination diseases, and neuropathic pain." (PMID 34385905, 2021).
chronic intestinal pseudo-obstruction (2 papers, 2022 to 2025). "Patients suffering from a severe motility disorder and chronic intestinal pseudo‐obstruction (CIPO) had reduced glial LPAR1 expression in their intestines." (PMID 39428750, 2025). "Samples from humans with chronic intestinal pseudo-obstruction (CIPO), a severe motility disorder, showed reduced glial LPAR1 expression in the colon and ileum." (PMID 35166239, 2022).
COVID-19 (2 papers, 2024 to 2025). A disease caused by infection with severe acute respiratory syndrome coronavirus 2. "In this regard, the study aimed to investigate the involvement of LPARs (specifically LPAR1, 3, 6) in the tri-directional relationship between AD, DM, and COVID-19 through network analysis, as well as explore the therapeutic potential of selected anti-AD, anti-DM drugs as LPAR, SPIKE antagonists." (PMID 38383841, 2024). "Overlapping genes for TSA and COVID-19 were SERPINH1, LPAR1, and TCEA2, and overlapping genes for TSA and MDD were NOL3, LPAR1, and HSPA6." (PMID 40918512, 2025). "Furthermore, we modeled the LPAR1, LPAR3, and LPAR6 in a complex with the COVID-19 spike protein and performed a docking study of selected drugs with the LPAR-Spike complex." (PMID 38383841, 2024).
demyelination diseases (2 papers, 2021 to 2022). "Moreover, dysregulation of LPAR1 has been associated with neurodevelopmental disorders, demyelination diseases, and neuropathic pain." (PMID 35682902, 2022).
Diabetic Nephropathy (2 papers, 2020 to 2022). "Since Ki16425 and BMS002 are antagonists of the LPA1 receptor and the LPA3 receptor, another study used the LPAR1-specific antagonist AM095 to research the function of the LPAR1 in diabetic nephropathy." (PMID 32284748, 2020). "In conclusion, these data suggest that LPA contributes to the pathogenesis of diabetic nephropathy by inducing EMT and renal tubular fibrosis via regulation of KLF5 through the LPAR1." (PMID 36142408, 2022).
glomerulosclerosis (2 papers, 2022 to 2023). A hardening of the kidney glomerulus caused by scarring of the blood vessels. "Simultaneously, another inhibitor of LPAR1/LPAR3 ameliorates albuminuria and glomerulosclerosis, the main pathological feature of type 2 DN." (PMID 35806457, 2022). "However, the administration of AM095, an LPAR1 inhibitor, attenuated the inflammatory response in STZ-induced diabetic mice, leading to a reduction in kidney weight, alleviation of albuminuria, and amelioration of glomerulosclerosis, thereby improving DN." (PMID 37373116, 2023).
lymph node metastasis (2 papers, 2019 to 2025). "This study not only confirmed the downregulation of LPAR1 in CC but also demonstrated that low positive expression of LPAR1 is associated with FIGO stage and lymph node metastasis." (PMID 41244534, 2025). "Similarly, low positive expression levels of LPAR1 were associated with FIGO stage (P=0.0024) and lymph node metastasis (P=0.0203)." (PMID 41244534, 2025). "Similarly, low positive expression of LPAR1 was correlated with FIGO stage (P=0.0024) and lymph node metastasis (P=0.0203)." (PMID 41244534, 2025).
multiple myeloma (2 papers, 2017 to 2018). "For example, during the progression of multiple myeloma, LPAR1 and LPAR3 transduce opposite signals to determine MSC fates as either myeloma supportive or suppressive stroma." (PMID 29898789, 2018).
neuropathy (2 papers, 2020 to 2022). A disorder affecting the nervous system that manifests with pain, tingling, numbness, and/or muscle weakness. "Blocking LPAR1 in mice promotes GI dysfunction that is reflected by decreased bowel transit and ENS structural alterations that indicate neuropathy and gliopathy." (PMID 35166239, 2022).
osteoporosis (2 papers, 2014 to 2018). A condition of reduced bone mass, with decreased cortical thickness and a decrease in the number and size of the trabeculae of cancellous bone (but normal chemical composition), resulting in increased fracture incidence. "In vitro and mouse studies additionally suggest potential application of LPAR1 antagonists in osteoporosis, which is notable given that osteoporosis is a frequent co-morbidity of COPD with an overall mean prevalence of 35.1%37." (PMID 30111857, 2018).
Parkinson disease (2 papers, 2019 to 2021). A progressive degenerative disorder of the central nervous system characterized by loss of dopamine producing neurons in the substantia nigra and the presence of Lewy bodies in the substantia nigra and locus coeruleus. "The effects of gintonin against Parkinson’s disease are mediated via Lpar1, and the Lpar1/Edg2 was downregulated in Parkinson’s disease rat model." (PMID 34385905, 2021).
peripheral nerve injury (2 papers, 2014 to 2022). Injury to a peripheral nerve. "Neuropathic pain was shown to be mediated by LPAR1, as mice lacking Lpar1 did not develop signs of neuropathic pain after peripheral nerve injury." (PMID 35959236, 2022).
pertussis (2 papers, 2021 to 2025). A contagious bacterial respiratory infection caused by Bordetella pertussis. "pertussis infection and highlight a novel LPAR1-dependent pathway for IFN-λ induction in the absence of type I IFN signaling." (PMID 40980929, 2025).
acute liver failure (1 paper, 2023). Rapid deterioration of liver function causing encephalopathy and coagulopathy. "Recently, the ATX-LPA axis was demonstrated to modulate the innate immune response in patients with acute liver failure via lysophosphatidic acid receptor 1 (LPAR1) and lysophosphatidic acid receptor 3 (LPAR3)." (PMID 37528089, 2023).
adenoma (1 paper, 2025). A neoplasm arising from the epithelium. "For instance, VRK1 showed a consistent upregulation in tumor/adenoma tissue with respect to adjacent mucosa, while WDR78, LPAR1, and RELL1 (the top three downregulated circRNA host genes in our dataset) decreased." (PMID 39980011, 2025).
Alcoholism (1 paper, 2015). "LPAR1 encodes a receptor for lysophosphatidic acid and has been associated with alcoholism (rs509276, located upstream of LPAR1; p = 2.5e-5 in Collaborative Study on the Genetics of Alcoholism COGA)." (PMID 26597164, 2015). "Of these 6 genes, LPAR1, PSD3, and GNAS are associated with brain-related phenotypes (alcoholism, memory, and brain waves), and LPAR1, PSD3, GNAS, and SRPK2 with eQTLs annotated in GTex or PheGenI in any human tissue (brain regions are not well represented in GTEx)." (PMID 26597164, 2015).
Apnea (1 paper, 2012). Lack of breathing with no movement of the respiratory muscles and no exchange of air in the lungs. "Among the top three SNPs for apnea-related traits identified in AAs, rs7030789 (LPAR1) showed evidence for association to an apnea phenotype in EAs with p = 0.01 for association to OSA and p = 0.06 to logAHI." (PMID 23155414, 2012). "Consistency of effects between rs7030789 and rs1409986 in LPAR1 and PTGER3 and apnea phenotypes were observed in independent clinic-based cohorts." (PMID 23155414, 2012).
astrocytomas (1 paper, 2021). "Although LPAR1 mRNA expression was associated with poor prognosis only in grade III astrocytomas, we were interested in evaluating whether there was a correlation between PGR and LPAR1 expression." (PMID 33916643, 2021). "For Kaplan–Meier curves, we found that LPAR1 low expression is the only one related to overall survival in astrocytoma grade III patients." (PMID 33916643, 2021). "Therefore, we constructed Kaplan–Meier graphs using TCGA data for astrocytoma grades II, III and IV with low and high expression of LPAR1, LPAR3 and ENPP2." (PMID 33916643, 2021). "Interestingly, using TCGA data base, we found that mRNA expression of LPAR1 increases according to tumor malignancy and correlates with a lower survival in grade III astrocytomas." (PMID 33916643, 2021).
atopic dermatitis (1 paper, 2021). "In skin diseases, however, LPA acts as a pruritogenic mediator through LPAR1 in atopic dermatitis model and induces itch through LPAR5." (PMID 34639115, 2021).
emphysema (1 paper, 2017). "We found that LPAR1-deficiency leads to alveolar enlargement or emphysema and decreased pulmonary vessel density in adult rats." (PMID 28382003, 2017). "Therefore, the adverse effect of a potent LPAR1 blocker on adverse alveolar development will probably be less severe when used postnatally in premature infants with BPD, thereby limiting the adverse effects on emphysema development in adult survivors of BPD." (PMID 28382003, 2017).
GI dysmotilities (1 paper, 2022). "Whether glial LPAR1 is dysregulated in the context of other GI dysmotilities, however, is an important next step that should be further investigated." (PMID 35166239, 2022).
Glucose intolerance (1 paper, 2024). Glucose intolerance (GI) can be defined as dysglycemia that comprises both prediabetes and diabetes. "We investigated a possible causal role for the elevated plasma LPA observed in male RT-SAKO mice in mediating reduced GLP-1 and insulin levels, and glucose intolerance, using Ki-16425, an LPAR1/3 antagonist." (PMID 38280449, 2024).
hematoma (1 paper, 2024). A hematoma is a collection of blood from a vascular structure into an extravascular space. "In terms of clinical risk factors, Logistic analysis showed that hematoma volume, Adropin, TXB2 and LPAR1 were all risk factors affecting the prognosis of HICH patients." (PMID 39697438, 2024). "The nomogram prediction model established based on hematoma volume, Adropin, TXB2, LPAR1 and other clinical risk factors as well as CT radiographic characteristics has high accuracy and prediction value in the diagnosis of poor prognosis in patients with HICH." (PMID 39697438, 2024). "In summary, the nomogram prediction model based on hematoma volume, Adropin, TXB2, LPAR1 and other clinical risk factors as well as CT radiographic characteristics has high accuracy and prediction value in the diagnosis of poor prognosis in patients with HICH." (PMID 39697438, 2024). "In Logistic multivariate analysis, hematoma volume, Adropin, TXB2, LPAR1 and CT radiological features were all independent factors influencing the poor prognosis of HICH (p < 0.05)." (PMID 39697438, 2024). "Compared with the good group, the hematoma volume in the poor group was significantly increased, the serum TXB2 and LPAR1 levels were significantly increased, and the Adropin level was significantly decreased (p < 0.05)." (PMID 39697438, 2024). "After Logistic multivariate analysis, hematoma volume, Adropin, TXB2, LPAR1, and CT radiological characteristics were all the independent factors influencing the poor prognosis of HICH (p < 0.05)." (PMID 39697438, 2024). "Compared with the good group, the hematoma volume in the poor group was significantly increased, the serum thromboxane 2(TXB2) and lysophosphatidic acid receptor 1(LPAR1) levels were significantly increased, and the energy balance related protein (Adropin) level was significantly decreased." (PMID 39697438, 2024).
hypertrophic cardiomyopathy (1 paper, 2025). A condition in which the myocardium is hypertrophied without an obvious cause. "Ablation of one of its receptors (lysophosphatidic acid receptor 1) exerts cardioprotective effects against hypertrophic cardiomyopathy in mice." (PMID 40312107, 2025).
ischemia (1 paper, 2024). A hypoperfusion of the BLOOD through an organ or tissue caused by a PATHOLOGIC CONSTRICTION or obstruction of its BLOOD VESSELS, or an absence of BLOOD CIRCULATION. "TXB2 and LPAR1 are both platelet activation products, which may promote platelet aggregation and aggravate the degree of ischemia and hypoxia of brain tissue." (PMID 39697438, 2024).
Jaundice (1 paper, 2019). Yellow pigmentation of the skin due to bilirubin, which in turn is the result of increased bilirubin concentration in the bloodstream. "A lower percentage of mice injected with LPAR1 knockout cells presented jaundice, liver tumor, and spleen invasion." (PMID 31668663, 2019).
keloid (1 paper, 2024). An irregularly shaped, elevated mark on the skin caused by deposits of excessive amounts of collagen during wound healing. "The downregulation of FOXF1 and LPAR1 in keloid patients could be caused by the inactivation of E2F1 and SP1 due to mutations or other factors, or by the effect of the three miRNAs." (PMID 38444850, 2024). "We therefore speculate that LPAR1 plays an important inflammatory and immune regulatory role in the formation of keloids." (PMID 38444850, 2024).
liver cirrhosis (1 paper, 2019). "To investigate whether LPAR1 is expressed on pathogenic collagen-producing cells in human liver cirrhosis, we interrogated the hepatic mesenchyme at single-cell resolution in a previously published dataset." (PMID 31722201, 2019).
mastitis (1 paper, 2023). Inflammation of breast tissue during lactation or postpartum due to an obstructed duct or infection. "In the MGI database, we found one gene disruption (Mfge8) and five transgenic mouse models for Lao1, Enpp2, Lpar1, Lpar2, and Lpar3 that resulted in abnormal mammary gland physiology and were also associated with mastitis." (PMID 36759924, 2023).
metastasis (1 paper, 2016). The spread or migration of cancer cells from one part of the body (where they first appeared) to another. "Besides that, LPAR1 expression was detected in all the 13 cases with abdominal metastasis more than 2 cm, 10 cases with retroperitoneal lymph node metastasis and 6 cases with hepatic metastasis." (PMID 27809800, 2016).
Miscarriage (1 paper, 2025). A pregnancy that ends at a stage in which the fetus is incapable of surviving on its own, defined as the spontaneous loss of a fetus before the 22th week of pregnancy. "For example, LPAR1 activation induces IL-8 via NF-κB, promoting endometrial angiogenesis, while disrupted LPA-LPAR signaling increases miscarriage rates in mice." (PMID 41199770, 2025).
oral carcinoma (1 paper, 2014). "Another oral carcinoma cell line, C12, which was employed for comparison, also strongly expressed LPAR1." (PMID 24928086, 2014).
vitiligo (1 paper, 2024). Generalized well circumscribed patches of leukoderma that are generally distributed over symmetric body locations and is due to autoimmune destruction of melanocytes. "Regarding ECA25, six significant genomic regions were identified, although genes related to biological processes associated with vitiligo (TXN, LPAR1, SLC46A2, PRPF4, TRIM32, STOM, BRINP1, and DAB2IP) were only found in five of them." (PMID 39199954, 2024).